SPSB3 (splA/ryanodine receptor domain and SOCS box containing 3)
Description:
Substrate-recognition component of a cullin-5-RING E3 ubiquitin-protein ligase complex (ECS complex, also named CRL5 complex), which mediates the ubiquitination and subsequent proteasomal degradation of target proteins, such as CGAS and SNAI1. The ECS(SPSB3) complex catalyzes 'Lys-48'-linked ubiquitination of nuclear CGAS in cycling cells, leading to its degradation. Recognizes and binds nucleosome-bound CGAS: ubiquitination and degradation of nuclear CGAS during G1 and G2 phases is required to promote low intranuclear CGAS abundance before the next mitotic cycle. The ECS(SPSB3) complex also mediates ubiquitination and degradation of phosphorylated SNAI1.
Synonyms: SSB-3; C16orf31; SSB3
Tractability: PROTAC: ubiquitination databases record sites on it.
Gene: Protein-coding gene on chromosome 16 (1,776,710 to 1,793,700, reverse strand). Ensembl gene ENSG00000162032.
Subcellular location: Nucleus
Subcellular location (Human Protein Atlas): Mitochondria
Pathways (Reactome):
Metabolism of proteins: Neddylation
Gene Ontology:
Molecular function: protein binding; ubiquitin-like ligase-substrate adaptor activity
Biological process: negative regulation of cGAS/STING signaling pathway; negative regulation of epithelial to mesenchymal transition; proteasome-mediated ubiquitin-dependent protein catabolic process; protein K48-linked ubiquitination; protein ubiquitination; ubiquitin-dependent protein catabolic process
Cellular component: Cul5-RING ubiquitin ligase complex; nucleus; cytosol; SCF ubiquitin ligase complex
Genetic constraint (gnomAD): Loss-of-function variants: 20 observed, 31.41 expected, observed/expected ratio (o/e) 0.64, 90% interval 0.45 to 0.93. The synonymous counts are far from expectation, so gnomAD's model fits this gene poorly and the ratio says little. Missense variants: 540 observed, 503.57 expected, observed/expected ratio (o/e) 1.07, 90% interval 1 to 1.15. Synonymous variants: 299 observed, 212.81 expected, observed/expected ratio (o/e) 1.4, 90% interval 1.28 to 1.55.
Homologues: Orthologues: chimpanzee SPSB3 (99% identical), macaque SPSB3 (99% identical), dog SPSB3 (90% identical), guinea pig SPSB3 (90% identical), rat Spsb3 (89% identical), pig SPSB3 (89% identical), mouse Spsb3 (89% identical), tropical clawed frog spsb3 (75% identical), zebrafish spsb3a (69% identical), Drosophila melanogaster CG10516 (28% identical). Paralogues in human: SPSB1 (20% identical), SPSB4 (18% identical), SPSB2 (17% identical), FBXO45 (17% identical).
Diseases named in the same sentence as SPSB3 in open-access papers:
SPSB3 is named in the same sentence as 7 diseases in open-access papers, as found by Europe PMC text mining. Sharing a sentence is not in itself a finding about the gene and the disease. The quoted sentences say what the papers report.
glaucoma (1 paper, 2016). Increased pressure in the eyeball due to obstruction of the outflow of aqueous humor. "Therefore we passed on the mentioned adjustments and consider the detected alterations in anti-AP1M1 ab and anti-SPSB3 ab over time in POAG + ODH as valuable hints to answer the question whether or not autoabs are relevant to glaucoma progression." (PMID 28030545, 2016).
malaria (1 paper, 2021). Malaria is a serious and sometimes fatal disease caused by a parasite that commonly infects a certain type of mosquito which feeds on humans. "Within the nine genes, five genes (MBP, SAMSN1, PSMF1, SLC39A8, and EIF3B) were previously found to be involved in malaria, and the remaining four genes (SMPDL3A, FABP5, SPSB3, and SHARPIN) were identified for the first time in the current study." (PMID 33942992, 2021). "Conversely, the other five key genes (MBP, SPSB3, PSMF1, SHARPIN, and EIF3B) were negatively correlated with malaria severity and decreased in CM." (PMID 33942992, 2021). "SAMSN1, SLC39A8, SMPDL3A, and FABP5 were positively correlated with malaria phenotype/severity and showed an upregulation in the CM group compared with healthy controls, while MBP, SPSB3, PSMF1, SHARPIN, EIF3B were negatively correlated with malaria severity and downregulated in the DEG." (PMID 33942992, 2021).
cancer (3 papers, 2019 to 2025). A tumor composed of atypical neoplastic, often pleomorphic cells that invade other tissues. "In the present study, we first found that SPSB family proteins SPSB2 and SPSB3 inhibit HCV replication, in addition to their other roles in cellular immune response and cancer invasion and metastasis." (PMID 31344133, 2019). "SPSB3 targets SNAIL for polyubiquitination and proteasomal degradation to suppress tumor metastasis in various kinds of cancer, suggesting the vital role of SPSB3 in regulating epithelial-mesenchymal transition and cancer progression." (PMID 31344133, 2019).
infection (1 paper, 2024). The state of being infected such as from the introduction of a foreign agent such as serum, vaccine, antigenic substance or organism. "By contrast, enforced degradation of cGAS by SPSB3 overexpression increased the susceptibility of the cells to infection with both HSV-1 and VACV." (PMID 38418882, 2024). "Interference with SPSB3-regulated nuclear cGAS degradation primes cells for type I interferon signalling, conferring heightened protection against infection by DNA viruses." (PMID 38418882, 2024).
SPSB3 also shares sentences with these, for which no sentence is quoted: esophageal cancer (1 paper); Sepsis (1); tumor (1).